BCL2 (BCL2 apoptosis regulator)
Diseases named in the same sentence as BCL2 in open-access papers (continued):
Sharing a sentence is not in itself a finding about the gene and the disease.
tumor (continued). "The expression analysis showed that ESR1 had no expression difference between normal and tumor groups; BCL2 expression was lower in tumor group (P < 0.001); while AKT1, CCND1, and HIF1A expressions were higher in tumor group compared with those in normal group (all P < 0.001)." (PMID 40552073, 2025). "We found that Bcl-2, an inhibitor of apoptosis, was downregulated in LCOR overexpressed cell lines, indicating that p38 exerted pro-apoptotic function rather than pro-tumor efficacy." (PMID 40083699, 2025). "The tumor cells were negative for SMA, CD34, bcl-2, ALK, and BCOR." (PMID 39857780, 2025). "Tumor cells were negative for S100 and positive for CD10 and BCL2 in their mesenchyme." (PMID 40831926, 2025). "Tumor cells express desmin and CD34 but are negative for CD99, Bcl-2, and STAT6." (PMID 39206171, 2024). "However, hormone-related genes (BAG1, BCL2, CD68, ESR1 (ER), GSTM1, PGR, SCUBE2) do not show significant differential expression among all tumor samples." (PMID 38254834, 2024). "Interestingly, one tumor cell line, defined as atypical, without SS18-SSX fusion and Bcl-2 expression was resistant to the combination therapy." (PMID 37720343, 2023). "However, venetoclax treatment of tumor-bearing mice or AML patients failed to deplete DCs, and Bcl2-/- de-ini-DCs that were transferred into NSCLC-bearing mice infiltrated tumors more efficiently than their WT counterparts." (PMID 37623817, 2023). "The Bcl-2 expression in SFT could prompt for targeted therapy, but due to the rarity of this tumor, there is a lack of randomized control trials and no consensus on treatment." (PMID 37720343, 2023). "The tumor cells were negative for MYC and BCL2 translocation." (PMID 37884941, 2023). "Second, we did not evaluate the cell of origin, BCL2/MYC expression, and/or tumor translocation." (PMID 35846027, 2022). "Western blot analysis of the tumor tissue samples also showed that the expression levels of cleaved caspase 3 and Bax were dose-dependently increased following the treatment of OPE, while no significance in the expression of Bcl2 was observed." (PMID 35504024, 2022). "Besides that BCL2, FKBP8, and KDM1A were increased in tumor compared with normal tissues, we also observed significant correlation between KDM1A and BCL2 protein level." (PMID 35970393, 2022). "We found that in tumor tissues with circ_0017109 knockdown, FZD4, β-catenin and non-phospho β-catenin, cyclin D1, and c-Myc showed significant reduction, and a higher level of cleaved caspase-3 and a lower level of Bcl-2 were also detected." (PMID 36434577, 2022). "We thus propose a simple model in which the LMP1-induced BNIP3 through ERK/HIF1α are crucial to the disruption of an interaction between Bcl-2 and Beclin1, thereby releasing the negative autophagic blockade, and further triggering the radioresistance of the NPC tumor." (PMID 33795637, 2021). "Groups of mice were treated either with the BCL-2 inhibitor ABT-199 (Venetoclax), or the conventional chemotherapeutic drug Cytarabine at doses that do not significantly reduce tumor burden in mice." (PMID 34580292, 2021). "Tumor cells are usually negative for CD5, CD23, CD138, Bcl-2, and TdT." (PMID 33322508, 2020). "The tumor cells stained positive for CD20 and BCL2 but negative for TdT, CD10 and EBER." (PMID 33339535, 2020). "The MFB tumor cells show immunoreactivity for CD34, desmin, and, variably, with smooth muscle actin (SMA), estrogen receptor (ER)/progesterone/androgen receptor, CD99, B-cell lymphoma 2 (Bcl2), and CD10, and they do not express cytokeratins or p63." (PMID 30989009, 2019).
tumor (continued). "Finally, treatment with rapamycin induced LC3-II, ATG7, ATG12 and Bcl2 expression and reduced the levels of SQSTM1/p62 and Bax, indicating that autophagy can protect tumour cells from the negative effects of HMGA2 knockdown." (PMID 31053152, 2019). "The Western blotting showed a down‐regulated expression of MARCH1, PI3K, P‐AKT, β‐catenin, Bcl‐2 and Mcl‐1 and an up‐regulated expression of pro‐apoptosis‐related Cleaved caspase‐3 and Cleaved caspase‐7 in the HCC tumours injected with MARCH1 siRNA compared with the negative controls." (PMID 30793486, 2019). "The neoplasms are negative for the following: CD5, CD23, BCL-2, and TdT." (PMID 29593916, 2018). "The MIB-1 labeling index was < 5% and tumor cells were negative for CD34 and bcl-2." (PMID 29168109, 2018). "Similarly, MCF7-LTED xenograft growth (tumor volume) was not affected by daily ABT-263 treatment, even though Bim/Bcl-2 interactions were disrupted by ABT-263." (PMID 29343814, 2018). "The tumor cells were diffusely positive for cytokeratin, EMA, and vimentin, and negative for bcl-2." (PMID 27068820, 2016). "Multivariate analysis was performed taking menopausal status at the time of diagnosis, tumor size, nodal status, grade, ER status, PR status, HER2 status, and Bcl-2 status into consideration in the patient group without adjuvant therapy and in the group with adjuvant tamoxifen monotherapy." (PMID 26472348, 2015). "In case 1, the expression of BCL-2 was quite high, which could account for inhibition of BECLIN 1 proautophagic activity, and in fact this tumour was negative for LC3 staining." (PMID 25136588, 2014). "While Bcl-2-mediated mitochondria-associated intrinsic cell survival pathway was significantly inhibited in PC3 cells and tumor xenografts by simvastatin treatment, over-expression of PC3 cells with Bcl-2 and/or dominant negative caspase 9 did not reverse the simvastatin-mediated PC3 cell apoptosis." (PMID 22974127, 2012). "However, whereas in many studies antiapoptotic Bcl-2 proteins or BH3 mimetics have been investigated in several cancer types, comparative studies with non-malignant cells to evaluate tumor-specific effects are surprisingly rare." (PMID 22292048, 2012). "Therefore, our results implied that exposure to the EMF of 1950-MHz TD-SCDMA may not promote the tumor formation, but continuous exposure damaged the mitochondria of astrocytes and induce apoptosis through a caspase-3-dependent pathway with the involvement of bax and bcl-2." (PMID 22870319, 2012). "Immunohistochemical staining demonstrated that most tumor cells were positive for B- cell markers such as CD20, bcl-6, and multiple myeloma oncogene 1 (MUM1), whereas those same tumor cells were negative for CD3, CD5, CD10, or bcl-2 (data not shown)." (PMID 22927863, 2012). "The reasons for this vary, but may include a lack of expression of TRAIL receptors on tumor cells, inadequate caspase activation after TRAIL receptor ligation, or over-expression of antiapoptotic molecules such as Bcl-2." (PMID 19547714, 2009). "BCL-2 and MEK1 expressions did not correlate with tumour grade." (PMID 12644821, 2003).
tumor (continued). "Nevertheless, the fact that in our study the expression of anti-apoptotic BCL-2 was not restored in repaired subclones suggests that enhanced ADCC after MYC modulation is not solely influenced by BCL-2, highlighting the multifaceted mechanisms of MYC to escape from anti-tumor immune responses." (PMID 39596160, 2024). "Indeed, differential gene expression analysis showed that BCL-2 expression was very low in LUAD cells, resulting in unstable expression, which may be why the difference in BCL-2 expression in mouse tumor cells was not significant." (PMID 37670265, 2023). "As a potent inducer of DNA damage in targeted tumor cells, it is anticipated that 225Ac‐lintuzumab may mediate effective down‐modulation of MCL‐1 leading to a sensitization of AML cells to venetoclax irrespective of inherent resistance to the BCL‐2 inhibitor." (PMID 33347715, 2021). "The treatment of tumor cells by HAMLET results in their apoptotic changes, such as caspase activation, phosphatidyl serine externalization, and chromatin condensation, but caspase inhibition or Bcl-2 over-expression not prolongs cell survival and the caspase response is Bcl-2 independent." (PMID 32825311, 2020). "All signaling pathway inhibitors have pronounced negative effects on the viability of both GBM tumor cell lines but U87MGvIII is significantly more sensitive to the inhibition of casein kinase than the wild-type whereas the wild-type is more sensitive to the inhibition of PLCG1, ABL1 and BCL2." (PMID 31386654, 2019). "There was very low or no expression of ki67 protein in residual tumor as compared to high expression of TFF3 in residual tumor cells suggesting that residual tumor cells have a low proliferating activity, this is supported by the high expression of Bcl2 and p-AKT-1 by residual tumor cells." (PMID 30744593, 2019). "Moreover, RNA-seq data from each of 40 advanced PDAC tumor specimens from the TCGA data base indicate a negative correlation between expression of miRNA-125b and five of six potential target genes (BAP1, BBC3, NEU1, BCL2, STARD13)." (PMID 25184537, 2014). "As we did not observe increased BCL-2/BCL-xL levels upon VPA/HU treatment potentially neutralizing increased BIM expression, it is conceivable to speculate that the addition of BH3 mimetics, such as ABT-737, may not further boost tumor cell death." (PMID 22289787, 2012). "Our work therefore highlights the need to assess whether patients’ tumor cells are functionally resistant to BCL-2 inhibition with techniques such as BH3 profiling, and if that is the case, to explore switching to CD47 blockade alone rather than combining with a BCL-2 inhibitor." (PMID 41484790, 2026). "However, the levels of anti-apoptotic machinery members (BCL-2, BCL-XL and MCL-1) were not dramatically affected indicating the strong tumor cell inhibition and induction of apoptosis in EC cells by ABT263 may be due to other mechanisms in addition to its canonical anti-BCL2 family." (PMID 26317542, 2015).
cancer (4,482 papers, 1994 to 2026). A tumor composed of atypical neoplastic, often pleomorphic cells that invade other tissues. "The cancer research field has extensively studied BCLAF1 as a transcription factor that binds to Bcl2 among the genes that frequently undergo mutations." (PMID 41487403, 2026). "SHBG downregulates the proto-oncogenes c-Myc, B-cell lymphoma-2 (Bcl-2), and growth factor receptors associated with cancer cell growth, proliferation and survival." (PMID 41586225, 2025). "For instance, overexpression of anti-apoptotic BCL2 proteins is linked to cancer development, resistance to therapy, and disease progression." (PMID 41155156, 2025). "The B Cell Lymphoma-2 (BCL-2) family proteins are central regulators of apoptosis, and their dysregulation is frequently associated with cancer progression and resistance to therapy." (PMID 40643466, 2025). "Apoptosis via the intrinsic mitochondrial pathway, characterized by increased B-cell lymphoma-2-associated X protein (BAX), reduced B-cell lymphoma-2 (BCL-2), and activation of caspase-3, is a widely recognized mechanism of effective anti-cancer agents." (PMID 41477125, 2025). "Dysregulation of apoptosis is a hallmark of cancer, often involving the overexpression of anti-apoptotic proteins (e.g., Bcl-2, Akt) and suppression of pro-apoptotic factors (e.g., Bax, Bim)." (PMID 40076649, 2025). "BCL2 is a critical regulator of intrinsic and extrinsic pathways of apoptosis that have been implicated in cancer progression and therapeutic resistance." (PMID 40136517, 2025). "c-MYC is a group of proto-oncogenes and regulator genes that encode transcription factors, whereas Bcl-2 is overexpressed in cancer cells and inhibits pro-apoptotic signals to enable cancer cells to survive in adverse conditions." (PMID 39852063, 2025). "Overexpression of anti-apoptotic members such as BCL-2 is a hallmark of various cancers and is associated with treatment resistance." (PMID 40643466, 2025). "BCL-2 proteins are key regulators of apoptosis, and their overexpression is often associated with resistance to chemotherapy in various cancers." (PMID 41465610, 2025). "The Bax/Bcl2 ratio mediates apoptosis by regulating mitochondrial integrity, and its dysregulation is implicated in both cancer and neurodegenerative diseases." (PMID 40407536, 2025). "Elevated BCL-2 levels due to aging increase cellular resistance to apoptosis, while age-related decline in DNA repair capacity contributes to long-term cancer risk." (PMID 40277546, 2025). "Immunohistochemical analysis revealed that AND downregulated key proteins associated with cancer cell proliferation and survival, including Ki67, B-cell lymphoma 2 (BCL-2), and Erythroblast transformation-specific-related gene (ERG)." (PMID 39937205, 2025). "Studies have shown that BCL2 expression is linked to cancer progression, specifically liver metastases of CRC." (PMID 39735667, 2025). "A more recent report on CLL patients with dual resistance to BTK inhibition and Bcl-2 antagonism has identified emerging BCL2 mutations in 4 out of 11 cases, with only 2 characterized by a mutated cancer cell fraction above 25%." (PMID 41213958, 2025). "Numerous studies have suggested that Bcl-2 is a favorable prognostic marker, with its expression generally associated with improved cancer patient outcomes." (PMID 40181963, 2025). "SDT has also been shown to reduce Bcl-2 expression, increase Bcl-2-associated X protein (Bax) expression, and induce apoptosis in cancer cells." (PMID 40698351, 2025).
cancer (continued). "Although GC are known to induce apoptosis in cancer cells, RA-derived T cells are resistant to GC-induced apoptosis, associated with upregulation of BCL-2." (PMID 41230096, 2025). "Stabilization of this G4 structure has been associated with transcriptional repression of BCL-2, thereby potentially inhibiting cancer cell proliferation." (PMID 41226615, 2025). "The upregulation of BCL-XL and BCL-2 is associated with acquired chemoresistance as cancer cells harness this mechanism to evade apoptosis." (PMID 40649963, 2025). "This alteration is in line with research showing that DZN inhibits the production of cyclin D1 and Bcl-2, which causes cancer cells to undergo cell cycle arrest and apoptosis." (PMID 40217305, 2025). "For example, 8 of the top 10 miRNAs most strongly associated with BCL2 expression across all cancers in iModEst have been shown to functionally regulate the BCL2 gene in previous literature." (PMID 40041206, 2025). "BCL2 overexpression is often observed in cancer cells and is associated with resistance to cytotoxic therapy." (PMID 40725171, 2025). "BCL-2 is responsible for inhibiting programmed cell death, and its overexpression is often associated with cancer resistance to treatment." (PMID 40286078, 2025). "In contrast, the overexpression of Bcl-2 (anti-apoptotic protein) is associated with resistance to chemotherapy in cancer cells." (PMID 41425711, 2025). "BCL-2, initially identified as the first anti-death gene, is implicated in cancer through various mechanisms such as chromosomal translocations, gene amplification, and altered expression regulation." (PMID 39193333, 2024). "By identifying pathogenic SNPs and their effects on Bcl-2, the study enhances understanding of the molecular mechanisms underpinning apoptosis resistance in cancer." (PMID 39840282, 2024). "The protein Bcl-2, well-known for its anti-apoptotic properties, has been implicated in cancer pathogenesis." (PMID 38978121, 2024). "BCL-2 and its close relatives enforce cellular survival and have been implicated in the development and progression of various cancer types." (PMID 39497108, 2024). "The largest cluster, which contains all the cancer types, is dominated by driver gene BCL2 as it mutates in 126 samples, indicating that BCL2 has a significant role in driving multiple cancer types." (PMID 39040139, 2024). "B-cell lymphoma gene 2 (Bcl-2) is the anti-apoptotic gene that prolongs cell survival by inhibiting apoptosis and is associated with the aggressive behaviour of malignant tumours." (PMID 39252711, 2024). "GO also listed pathways already known to be linked to Bcl-2 function such as Cell Cycle, MicroRNA in Cancer, Resistance to Drugs, Ras and PI3-Akt Pathways." (PMID 38755629, 2024). "Dysregulation of Bcl-2 is linked to various cancers, including lymphomas and solid tumors, and is associated with poor prognosis and treatment resistance." (PMID 39770021, 2024). "Bcl-2 overexpression or aberrant expression has been associated with many cancers’ emergence, progression, and relapse." (PMID 39840282, 2024). "BCL2 is an anti-apoptotic protein that prevents intended cell death, and its overexpression has been linked to several cancers, including lymphomas, leukemias, and breast cancer." (PMID 38352075, 2024). "BCL-2 family proteins that inhibit cell death include MCL-1, BCL-xL and BCL-2, and their expression has been implicated in poor cancer patient outcome and resistance to treatment." (PMID 39497108, 2024). "Information presented here on how SNPs in Bcl-2 influence protein-protein interactions can provide insights into the molecular mechanisms underlying cancer development and progression." (PMID 39840282, 2024).